LEP (leptin)
Diseases named in the same sentence as LEP in open-access papers (continued):
Sharing a sentence is not in itself a finding about the gene and the disease.
ovarian cancer (continued). "Leptin, but not OB3, induced the proliferation of ovarian cancer cells." (PMID 28750624, 2017). "Coincidently, leptin, but not OB3, increased circulating levels of follicle-stimulating hormone (FSH) which is known to play important roles in the initiation and proliferation of ovarian cancer cells." (PMID 28750624, 2017).
rheumatoid arthritis (76 papers, 2006 to 2025). A chronic, systemic autoimmune disorder characterized by inflammation in the synovial membranes and articular surfaces. "As a cytokine, leptin promotes a low-grade pro-inflammatory state, increasing the risk of type II diabetes, cardiovascular events, and autoimmune disorders such as rheumatoid arthritis (RA) and systemic lupus erythematosus (SLE)." (PMID 39409194, 2024). "Leptin has been implicated in promotion of auto-aggressive processes and autoimmune disease ranging from thyroid dysfunction, rheumatoid arthritis, Lupus erythematodes, autoimmune encephalitis and inflammatory bowel disease." (PMID 35216457, 2022). "It has also been observed that patients with rheumatoid arthritis have higher levels of leptin, and that leptin-deficient mice are less susceptible to antigen-induced arthritis." (PMID 27401171, 2016). "Adiponectin and leptin have recently emerged as potential risk factors in rheumatoid arthritis (RA) pathogenesis." (PMID 26681953, 2016). "While direct in vivo models of leptin-mediated autoimmune antibody production are limited, clinical evidence shows elevated leptin levels in human autoimmune diseases such as rheumatoid arthritis (RA), systemic lupus erythematosus (SLE) and MS." (PMID 41516046, 2025). "Due to its effect on inflammatory markers such as c-peptide, estrone, total estradiol, free estradiol, leptin, CRP, IL-6, sTNF-2, and total adiponectin, caffeinated coffee consumption was linked to an increased risk of rheumatoid arthritis." (PMID 39596082, 2024). "Adiponectin, leptin, and resistin are thought to be involved in the pathogenesis of rheumatoid arthritis (RA)." (PMID 37294817, 2023). "Adiponectin, leptin, and resistin are cytokines produced by the adipose tissue, so called adipokines, and they are thought to be involved in the pathogenesis of rheumatoid arthritis (RA), a chronic inflammatory disease." (PMID 37294817, 2023). "Leptin levels are related to autoimmune disorders such as multiple sclerosis, rheumatoid arthritis, systemic lupus erythematosus or inflammatory bowel diseases." (PMID 33673730, 2021). "Adiponectin, leptin, and resistin are adipocytokines whose levels are elevated in blood and synovial fluid from patients with rheumatoid arthritis (RA)." (PMID 33669910, 2021). "In this study, lower leptin levels were observed in synovial fluid compared to serum, similar to the results of other authors and to rheumatoid arthritis." (PMID 33803785, 2021). "Leptin was also detected in synovial fluid of patients with rheumatoid arthritis and OA and a positive correlation has been observed between its concentration in the synovial fluid and the severity of OA." (PMID 34440223, 2021). "Recently, increasing studies have revealed that leptin is involved in the development of rheumatoid arthritis (RA)." (PMID 33083462, 2020). "At the same time, the concentration of leptin in vitro experiments and OA/rheumatoid arthritis (RA) patients was summarized." (PMID 29620639, 2018). "Adiponectin and leptin have been recently considered to be important factors in rheumatoid arthritis (RA) pathogenesis." (PMID 26681953, 2016). "Some recent studies have shown elevated serum leptin levels in patients with systemic lupus erythematosus (SLE) or rheumatoid arthritis (RA) in comparison to healthy controls." (PMID 24900992, 2014). "Several adipokines other than RBP4 and including adiponectin, leptin and resistin can participate importantly in the pathophysiology of rheumatoid arthritis (RA), a prototypic inflammatory disease." (PMID 24651174, 2014). "Leptin antagonism reduced disease severity in a preclinical animal model of rheumatoid arthritis, and several studies have indicated that adiponectin is involved in the progression of RA." (PMID 23690663, 2013).
rheumatoid arthritis (continued). "Most of the data presented by different research groups showed changed levels of leptin, adiponectin, and resistin and occasionally also other adpokines in rheumatoid arthritis and systemic lupus erythematosus." (PMID 22584415, 2012). "In Otero's study, a marked increase levels of leptin in plasma was noted in patients with rheumatoid arthritis." (PMID 23144698, 2012). "Moreover, patients with rheumatoid arthritis show considerably higher plasma levels of leptin contributing to low-grade inflammation." (PMID 38419042, 2024). "In other diseases, a recent study of patients with rheumatoid arthritis found an association between leptin levels and pain, although the authors did not analyze the results by sex." (PMID 38792501, 2024). "In studies on patients with rheumatoid arthritis (RA), a hypothesis was proposed regarding a possible increase in the production of IL-8 and IL-6 induced by leptin." (PMID 38203376, 2023). "In addition to OA, leptin is reported to influence the pathogenesis of diseases such as rheumatoid arthritis (RA), ankylosing spondylitis (AS), systemic lupus erythematosus (SLE), or heterotopic ossifications of the posterior longitudinal ligaments and spine." (PMID 38139115, 2023). "Leptin is an inflammatory cytokine which was involved in the pathogenesis of rheumatoid arthritis and may be an indicator of disease activity and joint failure, as well as a potential therapeutic target." (PMID 35087951, 2022). "Leptin was also considered to play critical role in the pathology of human rheumatoid arthritis." (PMID 36405720, 2022). "It has been reported that elevated serum leptin levels could be found in OA and rheumatoid arthritis patients as compared with healthy subjects." (PMID 34440223, 2021). "For example, we previously reported that IL-6, rather than leptin, was highly elevated in patients with rheumatoid arthritis, which correlated with the generation of pathogenic TFH cells in this autoimmune disease." (PMID 34031386, 2021). "Higher leptin levels with an effect on chondrocytes via interleukin (IL)-1 regulation were found in the serum and synovial fluid of patients with osteoarthritis and rheumatoid arthritis." (PMID 32285743, 2020). "However, most of the studies are focusing on leptin with little research evaluating the role of adipokines with demonstrated actions in osteoarthritis and rheumatoid arthritis." (PMID 31027158, 2019). "Interestingly, the duration of rheumatoid arthritis ranged from 14 months to 17 years and leptin levels were highest in those with the shortest duration of disease." (PMID 29225423, 2017). "Furthermore, increased serum levels of different adipokines mainly leptin and adiponectin have been observed in several rheumatic autoimmune diseases such as rheumatoid arthritis (RA)." (PMID 28898254, 2017). "Moreover, leptin is also involved in the pathogenesis of rheumatoid arthritis (RA)." (PMID 39165638, 2024). "This study evaluated the effect of an individualized resistance exercise on inflammatory markers including leptin as well as muscle strength and exercise capacity in patients with rheumatoid arthritis (RA)." (PMID 35346353, 2022). "Leptin expression in serum and synovial fluid are related to degenerative diseases such as osteoarthritis (OA), rheumatoid arthritis (RA) and systemic lupus erythematosus (SLE)." (PMID 33673730, 2021). "Leptin has been identified as an important cytokine in the inflammatory networks of rheumatoid arthritis (RA)." (PMID 25009608, 2014). "Adiponectin and leptin are likely involved in the pathophysiology of rheumatoid arthritis (RA) and therefore potential new therapeutic targets." (PMID 23690663, 2013). "Furthermore, All-aca also inhibits leptin activity in some animal models of rheumatoid arthritis." (PMID 21771332, 2011).
rheumatoid arthritis (continued). "Thus, adipose tissue can secrete and release cytokines such as TNFα and IL-6, which are common in inflammatory diseases like rheumatoid arthritis (RA), as well as cytokines known as adipokines (leptin, adiponectin, resistin, and visfatin, among others)." (PMID 40077690, 2025). "A cross-sectional design of rheumatoid arthritis (RA) patients found that serum levels of NPY are significantly related to TNF-α levels and disease activity in RA independently of IL-6, TNF-α, or leptin levels." (PMID 35273572, 2022). "CpGs in this cluster have previously been reported to be related to the inflammatory disease rheumatoid arthritis, and IL1B and leptin are produced by the fat tissue as commented above." (PMID 36411288, 2022). "Leptin is significantly higher in synovial fluid of patients with OA and rheumatoid arthritis (RA)." (PMID 24086566, 2013). "Adipokines such as adiponectin, leptin, and visfatin/nicotinamide phosphoribosyltransferase (NAMPT) have recently emerged as pro-inflammatory mediators involved in the pathophysiology of rheumatoid arthritis (RA)." (PMID 24314299, 2013). "Leptin plays main actions in certain autoimmune diseases such as rheumatoid arthritis (RA)." (PMID 22910888, 2012). "All major adipokines (leptin, adiponectin, visfatin, and resistin) bear immune-modulatory properties and evidence points to involvement in the pathophysiology of rheumatoid arthritis (RA)." (PMID 22240096, 2012). "Rheumatoid arthritis (RA), multiple sclerosis (MS), autoimmune disease models and type 1 diabetes are all prevented in mice lacking leptin signalling." (PMID 40976999, 2025). "Plasma leptin levels were 13.7, 11.5, and 10.3 ng/ml in participants with rheumatoid arthritis, with osteoarthritis, and without arthritis, respectively (P = 0.34, n = 240)." (PMID 29225423, 2017). "Of 2,477 subjects in the NHANES III sample that had a hand examination and did not have rheumatoid arthritis, 1,056 (42.6%) had a leptin measurement and were included in the analysis." (PMID 22651805, 2012). "Anti-TNF-alpha therapy does not modulate leptin in patients with severe rheumatoid arthritis." (PMID 36291691, 2022). "Several studies have also reported increased leptin levels in systemic lupus erythematosus (SLE) and rheumatoid arthritis (RA) patients, and some have demonstrated their correlation with disease activity." (PMID 23259466, 2012). "However, in chronic inflammatory and infectiousdiseases such as AIDS, rheumatoid arthritis, and inflammatorybowel disease, no changes in leptin levels have beenobserved." (PMID 17497033, 2007). "We examined leptin and adiponectin concentrations and inflammatory markers such as metalloproteinase-3 (MMP-3) in 136 patients with rheumatoid arthritis (RA) (26 males and 110 females, 69.6 ± 9.3 years) and 78 controls (36 males and 42 females, 66.7 ± 15.0 years)." (PMID 32985609, 2020). "For example, a positive correlation between NPT and leptin was demonstrated in obese adolescents with NAFLD, while no such correlation was demonstrated in patients with rheumatoid arthritis." (PMID 41007299, 2025). "For example, although some authors have reported that leptin levels of SLE-patients and rheumatoid arthritis (RA)-patients are higher than those of normal controls, some others have found similar leptin plasma levels between SLE-patients and RA-patients with their respective controls." (PMID 23115723, 2012).
autoimmune disease (75 papers, 2007 to 2025). A disorder resulting from loss of function or tissue destruction of an organ or multiple organs, arising from humoral or cellular immune responses of the individual to their own tissue constituents. "Genes CPA3 and GATA2 expression were positively associated with levels of leptin, suggesting a genetic overlap between AN, autoimmune disease, and metabolic function." (PMID 39462405, 2024). "It has been previously reported that serum leptin levels increase in some autoimmune diseases and that leptin levels are also associated with disease activity." (PMID 36161623, 2022). "In recent years, variations in leptin levels were implicated in the development of MS and other autoimmune diseases, as leptin was found to be a key modulator of the immune system." (PMID 35328802, 2022). "Elevated levels of circulating leptin have also been associated with acute infections and certain autoimmune diseases, including immune thrombocytopenia (ITP)." (PMID 34299256, 2021). "It is interesting to know that, among ob/ob or DB/DB mice, susceptibility to autoimmune diseases is low because leptin appears to play a role in the development of several autoimmune disorders." (PMID 35027962, 2021). "Leptin secreted from adipose tissue serves as an inflammatory mediator and subsequent development of leptin resistance make obese individuals more susceptible to autoimmune disease including MS." (PMID 33053739, 2020). "Consistently, it has been demonstrated that leptin-deficient mice showed resistance or less susceptibility to the development autoimmune diseases." (PMID 32824322, 2020). "In this negatively virtuous interplay, the high levels of leptin secreted by the adipose tissue are able to dysregulate the Treg cells and determine an increased risk of developing autoimmune diseases in obese patients." (PMID 31091785, 2019). "Recent reports have shown that caloric restriction (CR) (associates with a fall in plasma leptin levels) can significantly increase the overall survival in several experimental animal models of autoimmune diseases." (PMID 24778633, 2014). "In animal experiments leptin deficient mice are resistant to the induction of several experimentally induced autoimmune diseases." (PMID 24900992, 2014). "Downregulation of leptin or its deficiency has been shown to prevent Th1-mediated autoimmune diseases such as RA, autoimmune arthritis, and encephalomyelitis in mice." (PMID 20953376, 2010). "Together with the finding of enhanced proliferation of T(reg) cells observed in leptin- and ObR-deficient mice, these results suggest a potential for therapeutic interventions in immune and autoimmune diseases." (PMID 20368778, 2010). "Conversely, immune-mediated disorders such as autoimmune diseases are associated with increased secretion of leptin and production of proinflammatory pathogenic cytokines." (PMID 20368778, 2010). "Leptin augments proinflammatory responses and enhances susceptibility to autoimmune diseases, including UC, which implies that neutralizing leptin action using a leptin antagonist may ameliorate the disease symptoms." (PMID 33935782, 2021). "Leptin and LR antagonists (leptin mutants, leptin-derived peptides, neutralising antibodies and soluble LR variants) were shown to have a clear potential as therapeutics for the treatment of several autoimmune diseases and cancer." (PMID 30659329, 2019). "Recent clinical studies on autoimmune disease patients demonstrated that high serum leptin levels may play a causal role in the disease progression and could represent a diagnostic marker for clinical application." (PMID 31091785, 2019). "Leptin signaling has also been implicated in several other autoimmune diseases." (PMID 29868016, 2018). "Leptin is immunostimulatory, implicated in autoimmune disease, and targeting this hormone may be beneficial." (PMID 30337927, 2018). "Only the autoimmune disease associated adipokine leptin was downregulated." (PMID 30224928, 2018).
autoimmune disease (continued). "Both leptin and inflammatory cytokines are implicated in the development of autoimmune diseases." (PMID 25890172, 2015). "Leptin has been associated with autoimmune diseases, in particular with RA." (PMID 24799765, 2014). "Thus, autoimmune disorders are associated with increased secretion of leptin, whereas AN and BN are conditions of reduced leptin production." (PMID 24106499, 2013). "In autoimmune pathways, leptin promotes the differentiation and proliferation of Th1 and Th17 cells, which are central to the pathogenesis of autoimmune diseases." (PMID 40277935, 2025). "This proinflammatory action of leptin contributes to the imbalance between effector T cells and Tregs observed in autoimmune diseases." (PMID 40277935, 2025). "The pro‐inflammatory action of leptin is reflected in the dysregulation of the CD4+ T cell subset in many autoimmune disorders, which includes increased Th1 and Th17 responses and reduced Treg responses." (PMID 40976999, 2025). "In EAE, a mouse model for studying autoimmune disease of the CNS, leptin levels have been shown to surge before disease onset, correlating with increased macrophage and T cell activation." (PMID 41516046, 2025). "In autoimmune disease, leptin’s pro-inflammatory effects likely promote the persistence of autoreactive B cells." (PMID 41516046, 2025). "Subsequently, studies in animal models of autoimmunity showed that leptin promotes autoimmune disease progression and allergic responses." (PMID 38031726, 2023). "Studies have suggested that leptin is involved in the pathogenesis of several autoimmune diseases, including SLE, MS, and IBS, and particularly RA." (PMID 37834128, 2023). "While these studies support an important role for leptin in optimal immune responses, leptin has also been shown to have a detrimental effect on autoimmune disease progression." (PMID 38031726, 2023). "Most human studies examining the role of leptin in patients with autoimmune disease have been limited and reserved to extremely rare clinical cases." (PMID 36479348, 2022). "There is evidence that leptin affects inflammation by altering the balance of Th17/Treg cells in autoimmune diseases." (PMID 36339447, 2022). "Leptin has a role in promoting the development of inflammation in many autoimmune diseases such as gout, and osteoarthritis." (PMID 36339447, 2022). "Leptin is an important intermediary for the interaction between nutritional status and neuroendocrine-immune function in vivo, and the content of Leptin is closely related to the occurrence and development of various autoimmune diseases." (PMID 35087951, 2022). "Leptin has been found to be involved in the development and progression of many autoimmune diseases." (PMID 36339447, 2022). "Because of the potential adverse effects leptin, including its tendency to stimulate angiogenesis and carcinogenesis, and to aggravate autoimmune disease, the application of leptin to chronic disease has been severely limited." (PMID 35527735, 2022). "Both leptin excess and leptin deficiency, as well as leptin resistance, are correlated with different human pathologies, such as autoimmune diseases and cancers, making leptin and leptin receptor important drug targets." (PMID 34356668, 2021). "Leptin’s involvement in many peripheral biological functions, as well as in autoimmune diseases and cancer increased the interest for the design and development of leptin-based drugs acting as leptin-activity modulators." (PMID 34356668, 2021). "Actually, leptin has been considered a therapeutic target in autoimmune diseases using leptin antagonists." (PMID 32824322, 2020). "Leptin promotes autoimmune diseases and its blockage is protective (pegylated leptin antagonist mutant L39A/D40A/F41A; PEG-MLA)." (PMID 33603741, 2020). "Due to its strong effects on T cells, leptin participates in the pathological processes of a variety of inflammatory and autoimmune diseases." (PMID 33329579, 2020).